HNRNPA2B1 (heterogeneous nuclear ribonucleoprotein A2/B1)
Description:
Heterogeneous nuclear ribonucleoprotein (hnRNP) that associates with nascent pre-mRNAs, packaging them into hnRNP particles. The hnRNP particle arrangement on nascent hnRNA is non-random and sequence-dependent and serves to condense and stabilize the transcripts and minimize tangling and knotting. Packaging plays a role in various processes such as transcription, pre-mRNA processing, RNA nuclear export, subcellular location, mRNA translation and stability of mature mRNAs. Forms hnRNP particles with at least 20 other different hnRNP and heterogeneous nuclear RNA in the nucleus. Involved in transport of specific mRNAs to the cytoplasm in oligodendrocytes and neurons: acts by specifically recognizing and binding the A2RE (21 nucleotide hnRNP A2 response element) or the A2RE11 (derivative 11 nucleotide oligonucleotide) sequence motifs present on some mRNAs, and promotes their transport to the cytoplasm. Specifically binds single-stranded telomeric DNA sequences, protecting telomeric DNA repeat against endonuclease digestion (By similarity). Also binds other RNA molecules, such as primary miRNA (pri-miRNAs): acts as a nuclear 'reader' of the N6-methyladenosine (m6A) mark by specifically recognizing and binding a subset of nuclear m6A-containing pri-miRNAs. Binding to m6A-containing pri-miRNAs promotes pri-miRNA processing by enhancing binding of DGCR8 to pri-miRNA transcripts. Involved in miRNA sorting into exosomes following sumoylation, possibly by binding (m6A)-containing pre-miRNAs. Acts as a regulator of efficiency of mRNA splicing, possibly by binding to m6A-containing pre-mRNAs. Plays a role in the splicing of pyruvate kinase PKM by binding repressively to sequences flanking PKM exon 9, inhibiting exon 9 inclusion and resulting in exon 10 inclusion and production of the PKM M2 isoform. Also plays a role in the activation of the innate immune response. Mechanistically, senses the presence of viral DNA in the nucleus, homodimerizes and is demethylated by JMJD6. In turn, translocates to the cytoplasm where it activates the TBK1-IRF3 pathway, leading to interferon alpha/beta production. (Microbial infection) Involved in the transport of HIV-1 genomic RNA out of the nucleus, to the microtubule organizing center (MTOC), and then from the MTOC to the cytoplasm: acts by specifically recognizing and binding the A2RE (21 nucleotide hnRNP A2 response element) sequence motifs present on HIV-1 genomic RNA, and promotes its transport.
Synonyms: HNRPA2B1; HNRNPA2; HNRNPB1; HNRPA2; HNRPB1; IBMPFD2; OPDM2; OPMD2; RNPA2; SNRPB1
Tractability: Antibody: UniProt places it where antibodies can reach, with high confidence; its Gene Ontology location is reachable by antibodies, with medium confidence. PROTAC: UniProt records ubiquitination sites on it; ubiquitination databases record sites on it; its protein half-life has been measured.
Gene: Protein-coding gene on chromosome 7 (26,171,151 to 26,201,529, reverse strand). Ensembl gene ENSG00000122566.
Subcellular location: Nucleus; Nucleus, nucleoplasm; Cytoplasm; Cytoplasmic granule; Secreted, extracellular exosome; Nucleus (Isoform A2)
Subcellular location (Human Protein Atlas): Nucleoplasm
Pathways (Reactome):
Metabolism of RNA: Processing of Capped Intron-Containing Pre-mRNA; mRNA Polyadenylation; mRNA Splicing - Major Pathway
Disease: Dengue Virus-Host Interactions
Immune System: Gene and protein expression by JAK-STAT signaling after Interleukin-12 stimulation
Gene Ontology:
Molecular function: miRNA binding; molecular condensate scaffold activity; mRNA 3'-UTR binding; N6-methyladenosine-containing RNA reader activity; protein binding; RNA binding; single-stranded telomeric DNA binding; DNA polymerase binding; G-rich strand telomeric DNA binding; nucleic acid binding; pre-mRNA intronic binding
Biological process: miRNA transport; mRNA export from nucleus; mRNA processing; mRNA splicing, via spliceosome; primary miRNA processing; RNA transport; DNA geometric change; mRNA transport; positive regulation of telomere maintenance via telomere lengthening
Cellular component: catalytic step 2 spliceosome; cytoplasm; extracellular exosome; membrane; nucleoplasm; nucleus; ribonucleoprotein complex; spliceosomal complex; Cajal body; chromosome, telomeric region; nuclear matrix; extracellular region
Genetic constraint (gnomAD): Loss-of-function variants: 1 observed, 43.75 expected, observed/expected ratio (o/e) 0.0229, 90% interval 0.007 to 0.11. The synonymous counts are far from expectation, so gnomAD's model fits this gene poorly and the ratio says little. Missense variants: 205 observed, 416.97 expected, observed/expected ratio (o/e) 0.49, 90% interval 0.44 to 0.55. Synonymous variants: 210 observed, 132.69 expected, observed/expected ratio (o/e) 1.58, 90% interval 1.41 to 1.77.
Gene-disease validity (ClinGen):
ClinGen rates the evidence that HNRNPA2B1 causes each of these diseases.
inclusion body myopathy with early-onset Paget disease with or without frontotemporal dementia 2 (autosomal dominant): Moderate.
Cancer hallmarks: escaping programmed cell death (promotes); proliferative signalling (promotes); tumour promoting inflammation (promotes); invasion and metastasis (promotes)
Homologues: Orthologues: rat Hnrnpa2b1 (100% identical), chimpanzee HNRNPA2B1 (99% identical), dog HNRNPA2B1 (99% identical), guinea pig HNRNPA2B1 (99% identical), pig HNRNPA2B1 (99% identical), mouse Hnrnpa2b1 (99% identical), macaque HNRNPA2B1 (88% identical), tropical clawed frog hnrnpa2b1 (85% identical). Paralogues in human: HNRNPA3 (74% identical), HNRNPA1 (66% identical), HNRNPA1L3 (63% identical), HNRNPA1L2 (62% identical), HNRNPA0 (35% identical), HNRNPD (31% identical), MSI1 (30% identical), HNRNPDL (30% identical), MSI2 (30% identical), HNRNPAB (29% identical), DAZAP1 (29% identical), NUCLEOLIN (27% identical), and 24 more.
Diseases named in the same sentence as HNRNPA2B1 in open-access papers:
HNRNPA2B1 is named in the same sentence as 163 diseases in open-access papers, as found by Europe PMC text mining. Sharing a sentence is not in itself a finding about the gene and the disease. The quoted sentences say what the papers report.
breast carcinoma (61 papers, 2010 to 2026). "LSD1 deficiency reduced hnRNPA2B1 expression in breast cancer cells by decreasing the level of H3K9me2 demethylation in the promoter region of the hnRNPA2B1 gene." (PMID 38448424, 2024). "The diagnostic model has been constructed with the three m6A regulators, and the diagnostic value of Breast Cancer was well validated In TCGA (AUC = 0.964), GEO datasets also verified the potential signature of HNRNPA2B1 in the diagnosis of Breast Cancer." (PMID 37671941, 2023). "The results of this study presented that HNRNPA2B1 is a potential diagnostic and prognostic marker of breast cancer." (PMID 37671941, 2023). "In this study, we utilized multi-dimensional investigation to explore the underlying oncogenic mechanism of HNRNPA2B1 in breast cancer, including bioinformatical analysis and human tissues examination." (PMID 37671941, 2023). "HNRNPA2B1 was previously reported to be associated with a number of cancers, including liver cancer, breast cancer, lung cancer, cervical cancer, and pancreatic cancer." (PMID 35559023, 2022). "Previous studies have shown that HNRNPA2B1 is overexpressed in breast cancer tissue, and that its encoded protein can activate the STAT3 and ERK1/2 signaling pathways, thereby promoting the tumorigenic potential of cancer cells." (PMID 33628845, 2021). "High HNRNPA2B1 expression is associated with poor prognosis of breast cancer, P < 0.001." (PMID 37671941, 2023). "By Cox analysis, HNRNPA2B1 was a risk factor for the prognosis of breast cancer." (PMID 37671941, 2023). "Further results confirmed that AGAP2-AS1 is packaged into exosomes by hnRNPA2B1 and this way transfers trastuzumab resistance to sensitive breast cancer cells." (PMID 39925739, 2025). "Ultimately, it was proved that encapsulation of AGAP2AS1 into exosomes and its secretion outside breast cancer cells is done in an hnRNPA2B1-dependent manner." (PMID 39925739, 2025). "Alizarin Red S staining assays showed that exosomes from hnRNPA2B1 KD breast cancer cells inhibited the formation of calcium nodules, an effect that was reversed by exosomes from hnRNPA2B1 KD breast cancer transfected with miR-6881-3p mimics." (PMID 38448424, 2024). "In summary, LSD1 KD in breast cancer cells led to a decrease in H3K9me2 demethylation in the promoter region of hnRNPA2B1, resulting in its downregulation." (PMID 38448424, 2024). "RAW264.7 cells were used to analyze the effects of exosomes from control, hnRNPA2B1 KD and hnRNPA2B1 KD+miR-6881-3p mimics-expressing breast cancer cells on osteoclast differentiation." (PMID 38448424, 2024). "In summary, our results demonstrated that LSD1 controls the sorting of miR-6881-3p into exosomes by regulating expression of hnRNPA2B1, which remodels the pre-metastatic niche during breast cancer bone metastasis." (PMID 38448424, 2024). "HNRNPA2B1 was expressed at higher levels in breast cancer cell lines (e.g., COLO824, MDAMB468, DU4475) than in other BC molecular subtypes (e.g. HCC2218, SUM185PE)." (PMID 37671941, 2023). "Then, we further detected the expression of HNRNPA2B1 by immunohistochemical method, and analyzed the relationship between it and the prognosis of breast cancer by COX regression method." (PMID 37671941, 2023). "In this study, it was found that HNRNPA2B1 was significantly correlated with the level of immune cell infiltration in breast cancer, as well as with the Stromal Score, ESTIMATE Score and immune Score." (PMID 37671941, 2023). "Our study revealed that hnRNPA2B1-mediated exosomal transfer of tumor-suppressive miR-184-3p from breast cancer cells to macrophages was an important mediator of TNBCs progression, providing new insights into TNBCs pathogenesis and therapeutic strategies." (PMID 37957722, 2023). "It was found that the abnormal expression of HNRNPA2B1 was considerably related to the occurrence of breast cancer by lasso regression analysis." (PMID 37671941, 2023).
breast carcinoma (continued). "We found that HNRNPA2B1 was significantly differentially expressed in breast cancer and correlated with breast cancer prognosis and immune infiltration." (PMID 37671941, 2023). "Knockdown of hnRNPA2B1 restored tamoxifen and fulvestrant sensitivity in breast cancer cells and was involved in AKT and MAPK pathway activation." (PMID 37990246, 2023). "Intriguingly, the heterogeneous nuclear ribonucleoprotein A2/B1 (HNRNPA2/B1) was demonstrated to be increased in endocrine-resistant LCC9 breast cancer cells and modulating the miRNA transcriptome upon its overexpression in MCF-7 cells." (PMID 36076918, 2022). "To further confirm our findings, we knocked down or over expressed hnRNPA2B1 in breast cancer cell line MCF7, we observed decreased growth in shA2B1 MCF7 cells compared with shCtrl group, and increased growth in A2B1 MCF7 cells compared with Vec group." (PMID 36451863, 2022). "The result manifests the overexpressed HNRNPA2B1 and contributes to the reduction of certain miRNA, which leads to tamoxifen resistance in breast cancer cells." (PMID 36553003, 2022). "Using the TIMER and GEPIA2 tools, we found that HNRNPA2B1 is present in abnormally high levels in various tumor types, such as breast cancer, OC, and LUAD." (PMID 35529270, 2022). "Data from the National Cancer Institute's Clinical Proteomic Tumor Analysis Consortium (CPTAC) database presented that there were higher HNRNPA2B1 protein levels in breast cancer, OC, colon cancer, and LUAD (P < 0.001)." (PMID 35529270, 2022). "hnRNPA2B1 also reduces the sensitivity of breast cancer cells to chemotherapy drugs by regulating the alternative splicing of Bcl-x pre-mRNA." (PMID 35279145, 2022). "In tamoxifen-resistant LCC9 breast cancer cells, studies have determined that overexpressed m6A “reader” HNRNPA2B1 can upregulate and downregulate different miRNAs simultaneously and affect the downstream signalling pathways of these miRNAs." (PMID 35004679, 2021). "HNRNPA2B1, another splicing factor of breast cancer, is also significantly upregulated in human breast cancer tissues and cell lines." (PMID 34044876, 2021). "In breast cancer, hnRNPA2B1 can directly bind to the UAGGG locus of PFN2 mRNA to reduce its stability, and thereby, inhibit the metastasis of breast cancer." (PMID 34094986, 2021). "In trastuzumab-resistant breast cancer cells, hnRNPA2B1 is overexpressed or silenced, and exosome AGAP2AS1 expression is correspondingly up-regulated or decreased." (PMID 33987099, 2021). "Genome-wide miRNA sequencing was performed post the upregulation of HNRNPA2B1 in endocrine-resistant breast cancer cells." (PMID 34108450, 2021). "In trastuzumab-resistant breast cancer cells, hnRNPA2B1 is overexpressed or silenced, and exosome AGAP2AS1 expression is upregulated or downregulated." (PMID 33987099, 2021). "Knockdown of HNRNPA2B1 reduced breast cancer cell proliferation, induced apoptosis, and prolonged the S phase of the cell cycle in vitro." (PMID 34476221, 2021). "In the BCIP breast cancer database, patients with high HNRNPA2B1 expression (n = 30) had longer survival times than patients with low HNRNPA2B1 expression (n = 288)." (PMID 34044876, 2021). "In detail, HNRNPA2B1 overexpressed in endocrine-resistant breast cancer cells reduces the sensitivity to 4-hydroxytamoxifen and fulvestrant by upregulating miR-1266-5p, miR-1268a, and miR-671-3p and downregulating miR-29a-3p, miR-29b-3p, and miR-222." (PMID 32443966, 2020). "hnRNPA2B1 is overexpressed in human gastric cancer, breast cancer cells, pancreatic cancer cells, lung cancer cells and several other cancers." (PMID 33163396, 2020). "Differential expression of HNRNPA2B1 has been reported in breast cancer, PCa, pancreatic cancer, and non-small cell lung cancer." (PMID 32322560, 2020). "Knockdown of the hnRNPA2B1 gene can significantly inhibit the proliferation of breast cancer cells, induce apoptosis of cancer cells, prolong the cell cycle and induce cell cycle arrest in S-phase." (PMID 32463472, 2020).
breast carcinoma (continued). "In GSE70905, YTHDC1 (p < 0.05), IGFBP1 (p < 0.001), ALKBH5 (p < 0.001), WTAP (p < 0.001), YTHDF3 (p < 0.001) and HNRNPA2B1 (p < 0.001) were down-regulated in breast cancer to the adjacent." (PMID 33362863, 2020). "In line with the TCGA outcomes, up-regulated HNRNPA2B1 is concluded to promote breast cancer tumorigenic potential by activating extracellular-signal-regulated kinase 1/2 (ERK1/2), and signal transducer and activator of transcription 3 (STAT3)." (PMID 33362863, 2020). "In LCC9 breast cancer cells resistant to endocrine, the upregulated HNRNPA2B1 seems to play a more complex role in miRNA transcriptome regulation." (PMID 32443966, 2020). "Knockdown of hnRNPA2B1 decreases breast cancer cell proliferation, increases apoptosis, and prolongs the S phase of cells by inhibiting STAT3/ERK1/2 signaling." (PMID 33292526, 2020). "HNRNPA2B1 can promote the endocrine resistance of breast cancer cells by down-regulating mir-29a-3p, mir-29b-3p, and mir-222, up-regulating mir-1266-5p, mir-1268a, and mir-671-3p, to reducing the sensitivity to 4-hydroxytamoxiphenylamine and fulva statin." (PMID 33552994, 2020). "We further found that LSD1 KD led to the downregulation of hnRNPA2B1 in breast cancer cells." (PMID 38448424, 2024). "We next investigated whether hnRNPA2B1 KD breast cancer cells could inhibit osteoblast differentiation and promote osteoclast differentiation by downregulating miR-6881-3p level in exosomes." (PMID 38448424, 2024). "Together, these results demonstrated that exosomes from hnRNPA2B1 KD breast cancer cells inhibited the differentiation of osteoblasts and promoted osteoclasts by downregulating exosomal miR-6881-3p levels, which in turn promotes bone colonization of breast cancer cells." (PMID 38448424, 2024). "However, the aberrant expression of HNRNPA2B1 in Breast Cancer (BC) and its clinical significance still need to be further studied." (PMID 37671941, 2023). "However, contrary to the findings in other cancer studies, hnRNPA2B1 shows an inverse correlation with breast cancer (BC) metastasis, and patients with high HNRNPA2B1 expression exhibit better survival and prognosis." (PMID 37546413, 2023). "Notably, HNRNPA2B1 expression was increased to varying degrees in various clinical data of breast cancer patients." (PMID 37671941, 2023). "The phosphorylated HNRNPA2B1 levels were evaluated in breast cancer, OC, and LUAD." (PMID 35529270, 2022). "For example, in breast cancer, knocking down hnRNPA2B1 leads to apoptosis of tumor cells, so hnRNPA2B1 is an oncogene in glioblastoma development and therefore may serve as a predictor of glioblastoma patient survival." (PMID 36051357, 2022). "In tamoxifen-resistant breast cancer cells, HNRNPA2B1 was reported to be upregulated, which led to the hypothesis that HNRNPA2B1 facilitates endocrine resistance by affecting the expression of miRNA." (PMID 36553003, 2022). "The HNRNPA2B1 phosphorylation sites in breast cancer, OC, and LUAD were investigated." (PMID 35529270, 2022). "In contrast, breast cancer patients with high HNRNPA2B1 expression have worse survival." (PMID 34044876, 2021). "In addition, there are few studies about HNRNPA2B1, but according to our results and those from breast cancer studies, we believe that it is also an important regulator that promotes tumorigenesis." (PMID 33628845, 2021). "We calculated the amount of each splicing factor and found that the HNRNPA2B1 level was slightly lower in breast cancer patients and all other splicing factor levels higher; this difference reached significance for PTBP1 (p < 0.05), HNRNPK_ex89 (p < 0.05) and SRSF6 (p < 0.01)." (PMID 32756364, 2020). "The effect of hnRNPA2B1 on the occurrence and development of breast cancer may be through the role of STAT3 and ERK1/2-related signaling pathways." (PMID 32463472, 2020). "Zhou et al25 discovered that HNRNPA2B1 was over‐expressed in breast cancers, and the same conclusion could be drawn in lung cancers." (PMID 32485038, 2020).